GALNT6 (polypeptide N-acetylgalactosaminyltransferase 6)
Diseases named in the same sentence as GALNT6 in open-access papers (continued):
Sharing a sentence is not in itself a finding about the gene and the disease.
ovarian carcinoma (8 papers, 2017 to 2025). A malignant neoplasm originating from the surface ovarian epithelium. "In ovarian cancer, higher GALNT6 levels are significantly associated with poorer patient survival rates." (PMID 36553184, 2022). "Our results suggest that GALNT6 expression is associated with poor prognosis of ovarian cancer and enhances the aggressive behavior of ovarian cancer cells by regulating EGFR activity." (PMID 28388560, 2017). "To better elucidate the molecular mechanisms and biological pathways implicated in GALNT6-mediated effects in ovarian cancer cells, we used a cDNA microarray technology to analyze changes in gene expression and identify the molecular targets upon GALNT6 suppression." (PMID 28388560, 2017). "Collectively, these data revealed that GALNT6 expression is upregulated in ovarian cancer and that increased GALNT6 is associated with poorer prognosis on the endometrioid and clear cell subtypes of ovarian cancer." (PMID 28388560, 2017). "Upregulation of GALNT2 and GALNT6 resulted in enhanced migration and invasion of oral and ovarian cancer cells, in part by increasing O-glycosylation and activation of the EGFR." (PMID 35028012, 2022). "The downregulation of the MUC1 protein, observed in our study upon knocking down both the GALNT3 and GALNT6 genes, emphasizes its possible role in enhancing the malignant phenotype of ovarian cancer." (PMID 31071912, 2019). "GalNT6 is up-regulated in breast and ovarian cancer initiating the O-glycosylation of MUC1, which we identified as a major ligand of CLEC10A." (PMID 31455323, 2019). "To study the role of GALNT6 in ovarian endometrioid and clear cell carcinomas, we first analyzed GALNT6 expression in 5 ovarian cancer cell lines (2 endometrioid and 3 clear cells) using Western blotting." (PMID 28388560, 2017). "This study is the first to report that GALNT6 plays important roles in malignant behaviors of ovarian cancer." (PMID 28388560, 2017). "GALNT6 knockdown with two independent siRNAs significantly suppressed viability, migration, and invasion of ovarian cancer cells." (PMID 28388560, 2017). "Data retrieved from Oncomine database showed that only GALNT6, 12, 14 and 15 expression levels were up-regulated in ovarian carcinoma compared with normal ovarian surface epithelium." (PMID 28388560, 2017). "We discovered that GALNT6 knockdown suppressed ovarian cancer cell proliferation, migration and invasion." (PMID 28388560, 2017). "To better understand the molecular mechanisms by which GALNT6 gene expression affects ovarian cancer progression, we evaluated global gene expression in control and GALNT6-knockdown ES-2 cells." (PMID 28388560, 2017). "In this study, p-RTK array results showed that GALNT6 regulates the phosphorylation of multiple RTKs in ovarian cancer cells, especially EGFR." (PMID 28388560, 2017). "Knockdown of GALNT6 suppresses malignant phenotypes in ovarian cancer cells." (PMID 28388560, 2017). "Thus, it is very unlikely that GALNT6 enhances the aggressive phenotypes of ovarian cancer cells through the MUC1 pathway." (PMID 28388560, 2017). "In contrast, overexpression of GALNT6 enhanced ovarian cancer cell malignant phenotypes." (PMID 28388560, 2017). "Furthermore, an EGFR inhibitor, erlotinib, reversed the effects of GALNT6 overexpression on malignant behavior of ovarian cancer cells, indicating that EGFR is a key mediator of GALNT6 effects on ovarian cancer cells." (PMID 28388560, 2017). "However, the expression and role of GALNT6 in ovarian cancer are still unclear." (PMID 28388560, 2017). "Mechanistic investigation suggests that GALNT6 modifies EGFR O-glycosylation, thereby, regulating EGFR phosphorylation, which in turn modulates ovarian cancer cell malignant behaviors." (PMID 28388560, 2017). "Traditional chemotherapy and radiation therapy may also benefit from a combination of glycosylation-targeting approaches, as demonstrated by the inhibition of GALNT6 and GALNT14 expression in ovarian cancer." (PMID 41008983, 2025).
ovarian carcinoma (continued). "Moreover, GALNT6 modifies EGFR O-glycosylation and plays critical roles in malignant phenotypes of ovarian cancer cells." (PMID 28388560, 2017). "This is the first to show the correlation between GALNT6 and EGFR activity in ovarian cancer." (PMID 28388560, 2017). "In addition, knockdown of GALNT6 reduced Tn antigen expression on EGFR and decreased the phosphorylation of EGFR in ovarian cancer cells, suggesting that GALNT6 affects ovarian cancer progression by modifying EGFR activity." (PMID 28388560, 2017).
gastric cancer (7 papers, 2014 to 2023). A primary or metastatic malignant neoplasm involving the stomach. "Moreover, a low expression of TFF2 and TFF3, which were predicted to be inhibited by GALNT6, have been reported to associate with gastric cancer." (PMID 36748835, 2023). "Previously, it was shown that GALNT6 and GALNT15 expression were significantly upregulated in gastric cancer tissues and the high expression of GALNT6 was significantly correlated with a low expression of E-cadherin and β-catenin, as well as high expression of MMP9." (PMID 36429094, 2022). "Similarly, GALNT6 has been extensively studied for its oncogenic role in malignant diseases, such as breast, pancreatic, and gastric cancer." (PMID 31071912, 2019). "Thus, GALNT6 and GALNT13 display elevated levels in different cancer types, including breast and gastric carcinomas (GALNT6) and lung cancer and neuroblastoma (GALNT13), as both genes are found to be associated with tumor invasion and metastasis." (PMID 24504219, 2014). "In this study, we found that c-Myc directly facilitated the transcription of GALNT6 and MGAT1 in gastric cancer cells, leading to O-glycosylation or N-glycosylation and stabilization of FN1 and GLUT1 protein, respectively." (PMID 37993881, 2023). "For instance, GALNT3 was proposed as a marker of non-small cell lung cancer prognosis, whereas GALNT6 and GALNT14 itself were proposed as potential tissue biomarkers, since their high expression in breast and gastric carcinomas." (PMID 26309160, 2015). "Importantly, as a RBP, cytoplasmic NONO stabilizes GALNT2, GALNT6, and hnRNPU mRNA in gastric cancer cells, which is also repressed by circ-hnRNPU." (PMID 37993881, 2023). "In these gastric cancer cases, the expression of circ-hnRNPU, NONO, or c-Myc was negatively or positively correlated with that of target genes GALNT2, GALNT6, MGAT1, or hnRNPU." (PMID 37993881, 2023).
lung carcinoma (7 papers, 2014 to 2025). "In lung cancer, targeting glycosyltransferases like GALNT6, which initiates O-glycosylation of mucins, could disrupt mucin-mediated signaling pathways." (PMID 40655139, 2025). "Since distant metastasis is the key for lung cancer-related death, targeting GALNT6 may inhibit the metastasis of lung adenocarcinoma." (PMID 32393740, 2020). "Strikingly, three early EMT hallmark genes GALNT6, SPARC and HES7 show the similar stage-specific expression pattern in LUAD TCGA samples, which can be further studied for diagnosis of early stages of lung cancer and for developing anticancer drugs." (PMID 31296175, 2019). "We found that eRNAs chr12.51786511.51786834 and chr7.55132578.55133258 were located in close proximity to the oncogenes GALNT6 and EGFR, which promote metastasis and invasion of lung cancer cells." (PMID 34439379, 2021). "For example, we observed that eRNAs chr12.51786511.51786834 and chr7.55132578.55133258 were upregulated and located near GALNT6 and EGFR, which have been found to promote metastasis of lung cancer cells." (PMID 34439379, 2021). "Polypeptide N-acetylgalactosaminyltransferase-6 (GALNT6) O-glycosylates and stabilizes GRP78, which promotes EMT by enhancing the MEK1/2/ERK1/2 signaling in lung cancer cells." (PMID 33743739, 2021). "We also observed that GALNT6, GRP78, and p-ERK1/2 were upregulated in lung cancer tissues compared with adjacent normal lung tissues." (PMID 32393740, 2020). "GALNT6 knockdown in pancreatic cancer cells reduces MUC4 expression and alters cadherin switching from P-cadherin to E-cadherin, suggesting a similar strategy could be effective in lung cancer." (PMID 40655139, 2025).
pancreatic cancer (7 papers, 2011 to 2023). "The expression of GALNT6 was associated with advanced tumor stage, and had an area under curve (AUC) value of 0.919 in pancreatic cancer based on the cancer genome atlas (TCGA) dataset." (PMID 36925932, 2023). "In contrast, GALNT6 expression in pancreatic cancer is associated with better overall survival." (PMID 28388560, 2017). "Similarly, GALNT6 expression in pancreatic cancer is associated with better overall survival." (PMID 24504219, 2014). "The expression of GALNT6 in pancreatic cancer and normal tissues were analyzed by bioinformatic analyses and immunohistochemistry." (PMID 36925932, 2023). "Reports showed that dysregulation of GALNT3 and GALNT6 promote the metastatic phenotypes pancreatic cancer." (PMID 36925932, 2023). "Here, we confirmed that GALNT6 was overexpression in PDAC, associated with advanced tumor stage, and had an AUC value of 0.919 in pancreatic cancer based on TCGA dataset." (PMID 36925932, 2023). "GALNT3 was predicted as an independent prognostic factor in renal cell carcinomas, and GALNT6 was found to function in pancreatic cancer." (PMID 29970122, 2018). "Furthermore, the expression of GALNT6 was detected in a tissue microarray of 18 pairs of pancreatic cancer tissues and normal control tissues by IHC." (PMID 36925932, 2023). "We found that GALNT6 is highly expressed in pancreatic cancer and plays a carcinogenic role." (PMID 36925932, 2023). "The level of GALNT6 in pancreatic cancer tissues (n = 178) was significantly higher than that in normal control (n =171)." (PMID 36925932, 2023).
colorectal cancer (4 papers, 2019 to 2025). A primary or metastatic malignant neoplasm that affects the colon or rectum. "We found that loss of GALNT6 protein expression, as defined by <10% of tumor cells expressing GALNT6, predicts poor overall survival in early-stage colorectal cancer patients (stages I and II)." (PMID 35692787, 2022). "Using large cohorts of patients and different approaches, this study shows that loss of GALNT6 enzyme in early-stage colorectal cancer predicts poor clinical outcomes." (PMID 35692787, 2022). "In colorectal cancer, GALNT6 is identified as one of the susceptibility genes, and GALNT6 expression is involved in oncogenic transformation and progression." (PMID 35692787, 2022). "In summary, our study shows that loss of the GALNT6 enzyme occurs in a subset of early-stage colorectal cancer patients and is significantly associated with poor (G3) differentiation, right-sided location, lymphovascular invasion, MSI subtype, and shorter overall survival." (PMID 35692787, 2022). "It will be interesting to study whether colorectal cancers with loss of GALNT6 might show elevated expression of the negatively correlated mucins." (PMID 35692787, 2022). "To gain insights into GALNT6 protein expression in colorectal cancers, we examined 679 tumor specimens in tissue microarrays by immunohistochemistry." (PMID 35692787, 2022). "Given its crucial function in O-glycosylation of the colorectal mucus layer, we investigated GALNT6 as a potential marker of colorectal cancer, particularly of early-stage disease." (PMID 35692787, 2022). "To further investigate whether GALNT6 is an independent prognostic factor in early-stage colorectal cancer, we performed both univariate and multivariate analyses." (PMID 35692787, 2022). "Hence, these statistical analyses further support GALNT6 protein as a prognostic marker for poor survival in early-stage colorectal cancer." (PMID 35692787, 2022). "Lack of GALNT6 protein expression was also associated with poor therapeutic response to 5-FU-based adjuvant chemotherapy in colorectal cancer." (PMID 35692787, 2022). "To further understand GALNT6 expression in colorectal cancer, we investigated its relation with a number of clinicopathological features, including patient age and gender, histologic type, tumor grade, location, lymphovascular and perineural invasion, pTNM stage, and MSI/MSS subtype." (PMID 35692787, 2022). "GALNT6 protein expression vs. clinical features of colorectal cancer cases." (PMID 35692787, 2022). "Prognostic potential of GALNT6 protein expression in early-stage colorectal cancer." (PMID 35692787, 2022). "The functional role of GALNT6 in colorectal cancer remains unknown at present." (PMID 35692787, 2022). "In another study of 195 patients with stage II and III colorectal cancer, tumors lacking GALNT6 protein were associated with poorer histologic differentiation, and patients with negative GALNT6 had significantly poorer disease-free survival and overall survival." (PMID 35692787, 2022). "In a cohort of 84 colorectal cancer tissues and 77 normal non-tumor mucosal tissues, cancer patients with higher expression of GALNT6 protein had better overall survivals than those with lower expression." (PMID 35692787, 2022). "While 9.9% (57/574) of early-stage colorectal cancer cases were negative for GALNT6 expression, 15.2% (16/105) of late-stage cancers were GALNT6-negative." (PMID 35692787, 2022). "Interestingly, GALNT6 mRNA expression showed significant correlation with KRAS and BRAF status in early-stage colorectal cancers." (PMID 35692787, 2022). "Both GALNT3 and GALNT6 displayed oncogenic functions in different cancer types; GALNT3 has often been suggested as a possible therapeutic target in pancreatic, gastric, and colorectal cancers." (PMID 31071912, 2019).
colorectal cancer (continued). "This analysis identified five glycosyltransferase genes, namely, ST6GAL1, GALNT6, HPSE, GALNT1, and GALNT7, expression of which was consistently upregulated or downregulated in MSI colorectal cancer tissues, cell lines, and single epithelial cells compared with MSS colorectal cancers." (PMID 40824763, 2025). "Since GALNT6 belongs to a large family of N-acetylgalactosaminytransferases that initiate mucin-type O-glycosylation, we asked whether GALNT family enzymes are redundant in colorectal cancer." (PMID 35692787, 2022). "Furthermore, GALNT6-negative cases are more prevalent in the MSI subtype than in the MSS subtype of colorectal cancer." (PMID 35692787, 2022).
lung adenocarcinoma (4 papers, 2016 to 2024). A carcinoma that arises from the lung and is characterized by the presence of malignant glandular epithelial cells. "Furthermore, higher levels of GALNT6 expression were associated with poor overall survival of 720 patients with lung adenocarcinoma in database." (PMID 32393740, 2020). "Hence, high GALNT6 expression level was associated with poor prognosis of human lung adenocarcinoma." (PMID 32393740, 2020). "Conceivably, further identification of new substrates of GALNT6 is necessary to clarify the roles of GALNT6 in metastasis of lung adenocarcinoma." (PMID 32393740, 2020). "Mechanistically, GALNT6 over-expression in lung adenocarcinoma cells increased N-cadherin and Slug expression, but decreased E-cadherin expression while GALNT6 silencing had opposite effects." (PMID 32393740, 2020). "In the current study, we found that GALNT6 expression was upregulated in human lung adenocarcinoma tissues, which was significantly correlated with higher tumor stage, lymph node metastasis, TNM stage and poor prognosis." (PMID 32393740, 2020). "In clinical, cellular and animal studies, GALNT6 has been found to promote the invasion and metastasis of lung adenocarcinoma, but it is unclear how GALNT6 regulates the EMT process to promote tumor metastasis." (PMID 32393740, 2020). "GALNT6 silencing also mitigated the metastasis of lung adenocarcinoma and prolonged the survival of xenograft tumor-bearing mice." (PMID 32393740, 2020). "We then examined the capacity of GALNT6 to change migration and invasion of lung adenocarcinoma cells." (PMID 32393740, 2020). "GALNT6 was mainly located in the cytoplasm of tumor cells and 77.64% of lung adenocarcinoma tissues expressed high levels of GALNT6 as compared to 7% of adjacent non-tumor tissues (P < 0.001)." (PMID 32393740, 2020). "Kaplan–Meier analyses revealed that patients with high GALNT6 expressing lung adenocarcinoma had a significantly shorter survival than those with low GALNT6 expression (P = 0.006)." (PMID 32393740, 2020). "Three of the nine-examined early EMT hallmark genes, GALNT6, SPARC and HES7, were up-regulated specifically in the early stages of lung adenocarcinoma (LUAD) and confirmed by TCGA patient transcriptome data." (PMID 31296175, 2019). "We speculate that GALNT6 may directly interact with GRP78 to regulate the EMT process in lung adenocarcinoma cells." (PMID 32393740, 2020). "We further analyzed whether GALNT6 silencing may affect the metastasis of lung adenocarcinoma in vivo." (PMID 32393740, 2020). "Stratification analyses showed that higher GALNT6 expression in lung adenocarcinoma was significantly correlated with higher T stage (P = 0.017), positive lymph node metastasis (P = 0.024) and higher TNM stages (P = 0.001), but not with patient age, gender and differentiation grade." (PMID 32393740, 2020). "Therefore, GALNT6 is emerging as novel positive regulator for the malignancy of human lung adenocarcinoma." (PMID 32393740, 2020). "In this study, we found that GALNT6 enhanced EMT in lung adenocarcinoma cells." (PMID 32393740, 2020). "Consequently, GALNT6 promoted the in vitro wound closure and invasion as well as metastasis of lung adenocarcinoma in mice." (PMID 32393740, 2020). "Therefore, GALNT6 silencing inhibits the metastasis of lung adenocarcinoma in mice." (PMID 32393740, 2020). "Thus, GALNT6 enhances the migration and invasion of lung adenocarcinoma cells." (PMID 32393740, 2020). "Therefore, GALNT6 may promote EMT in lung adenocarcinoma cells in vitro." (PMID 32393740, 2020). "Currently, it is unclear how GALNT6 regulates the EMT process to promote invasion and metastasis of lung adenocarcinoma." (PMID 32393740, 2020). "GALNT6 directly interacted with GRP78 and its over-expression upregulated GRP78 and enhanced MEK1/2 and ERK1/2 phosphorylation and EMT in lung adenocarcinoma cells." (PMID 32393740, 2020).
lung adenocarcinoma (continued). "In this study, we found that GALNT6 O-glycosylated and stabilized GRP78, and enhanced the activation of MEK/ERK signaling in lung adenocarcinoma cells." (PMID 32393740, 2020). "By analyzing LUAD dataset from TCGA, we found three EMT markers (GALNT6, SPARC and HES7) among the nine in vitro identified genes with known function are also up-regulated in specifically in early stage lung adenocarcinoma patients." (PMID 31296175, 2019). "In lung adenocarcinoma cells, GALNT6 over-expression promoted epithelial–mesenchymal transition (EMT), wound healing, and invasion which could be significantly reversed by GALNT6 silencing." (PMID 32393740, 2020). "Our results may contribute to the development of potential strategies to target GALNT6/GRP78 and suppress metastasis of lung adenocarcinoma." (PMID 32393740, 2020). "However, it is unclear whether GALNT6 also O-glycosylates and stabilizes GRP78 in lung adenocarcinoma cells and to regulate EMT and metastasis." (PMID 32393740, 2020).
colon adenocarcinoma (2 papers, 2020 to 2021). "Additionally, the mRNA expression levels of GALNT6 were higher in colon adenocarcinoma tissues with GEPIA analysis." (PMID 35003361, 2021). "GALNT6 expression is highly upregulated in colon adenocarcinoma but absent in normal-appearing adjacent colon tissue, suggesting that abnormal expression of GALNT6 may be an early event in colon carcinogenesis." (PMID 32393740, 2020).